TTC41P (tetratricopeptide repeat domain 41, pseudogene)
Synonyms: GNN; GNNP
Gene: Transcribed unitary pseudogene on chromosome 12 (103,843,756 to 103,915,867, reverse strand). Ensembl gene ENSG00000214198.
Subcellular location: Cytoplasm